FLI1 (Fli-1 proto-oncogene, ETS transcription factor)
Diseases named in the same sentence as FLI1 in open-access papers (continued):
Sharing a sentence is not in itself a finding about the gene and the disease.
Ewing sarcoma (continued). "However, it is important to note that while FLI-1 is a sensitive marker for AS, its expression has also been detected in benign vascular tumors, such as hemangiomas, or other non-endothelial neoplasms, such as Ewing’s sarcoma, erythroleukemia, lymphoma." (PMID 40666093, 2025). "Ewing Sarcoma (ES) is a primitive small round cell sarcoma defined by fusions involving members of the FET (predominantly EWSR1 or FUS) and ETS (most commonly including FLI1, ERG, ETV1, ETV4, or FEV) gene families." (PMID 35059992, 2022). "One possible explanation is that there is no selectivity for specific chromosomes in the EWSR1/FLI1-dependent induction of aneuploidy, but during subsequent cell divisions, cells that inherit particular chromosomes manage to survive and expand during Ewing sarcoma development." (PMID 33293370, 2021). "Among the tested BSTS histotypes, Ewing’s sarcoma cells were the most sensitive to the combination, a result that might be explained by the known exquisite sensitivity of the pathognomonic fusion protein EWS/FLI1-expressing cells to both trabectedin and PARP1 inhibition." (PMID 28454547, 2017). "The first translocation identified in patients with Ewing sarcoma (ES) between the EWSR1 gene on chromosome 22q12 and FLI1 (Friend leukemia virus integration 1), a member of the ETS gene family of transcription factors on chromosome 11q24, was reported in 1992." (PMID 22665999, 2012). "Hence, EWS/FLI-1 siRNA induces apoptosis in TC-71 Ewing's sarcoma cells, while R1507 does not." (PMID 22022506, 2011). "For Ewing sarcoma, CD99 expression is sensitive but not specific and must be interpreted alongside FLI1, which improves specificity." (PMID 41458270, 2025). "Under these conditions, Cas9 is selectively expressed in Ewing sarcoma cells that express EWSR1 : : FLI1 oncoproteins, but not in cells expressing wild-type FLI1." (PMID 40089636, 2025). "Although bone marrow–derived MSCs can undergo transformation, and EWSR1::FLI1 silencing reverts 3D chromatin conformation toward an MSC-like architecture, Ewing sarcoma does not appear to co-opt canonical MSC lineage TFs as principal dependencies." (PMID 41444391, 2025). "Although low-dose HDAC inhibitors did not affect the level of EWS::FLI1 in our experiments, proteomic analyses identified that HDAC inhibitors do reduce the level of the BRD4 protein in Ewing sarcoma cell lines." (PMID 40478628, 2025). "Splicing analysis of published data in Ewing sarcoma cells with and without EWSR1::FLI1 identified 921 AS events." (PMID 36793594, 2023). "In non-permissive cell types, or when expressed too highly in Ewing sarcoma or permissive progenitor cells, EWS::FLI1 induces cell cycle arrest and death." (PMID 36505823, 2022). "On the other hand, they similarly analyzed the distance between the EWS and FLI1 loci in lymphocytes, which, they concluded, was larger than that between BCR and ABL48, although the precursor of Ewing sarcoma cells is not of lymphoid lineage." (PMID 36042341, 2022). "Activation of canonical Wnt/beta-catenin signaling in Ewing sarcoma cells results in derepression of TGFBR2 and creates an EWS::FLI1 “low” cell state without altering the level of the fusion protein." (PMID 36505823, 2022). "Atypical teratoid/rhabdoid tumor (AT/RT) and Ewing sarcoma (EWS) was excluded based on maintained INI1 expression and absence of the EWS/FLI1 translocation and CD99 expression." (PMID 26883117, 2016). "Ewing sarcoma (ES) on the other hand is characterized by a translocation involving the ubiquitously expressed, putative RNA-binding EWSR1 gene and the friend leukemia integration 1 (FLI1) transcription factor, forming the EWS/FLI1 fusion protein as the most common fusion event." (PMID 23761860, 2013). "Due to the lack of a good model system in Ewing's sarcoma, concerns have been raised about how well results from EWS/FLI-1 in murine cells will translate to human cells." (PMID 22523703, 2012).
Ewing sarcoma (continued). "A secondary benefit of employing GLI1 inhibition in Ewing tumors is that GLI1, unlike EWS/FLI1, is felt to be involved in the pathogenesis of a large number of common malignancies." (PMID 19859563, 2009). "Globally, the most common histological subtype was osteosarcoma (OS), all conventional high-grade OS, followed by Ewing sarcoma (EWS), all carrying EWS::FLI1 translocation (type 1 in 1 case, type 2 in 2 cases, and not determined in 2 cases), and other rare tumors." (PMID 41514647, 2025). "It should be noted that SEs are typically absent at the EWSR1, FLI1, and ERG loci in Ewing sarcoma." (PMID 41444391, 2025). "However, the fusion oncogene is not part of our Ewing sarcoma CRC since SEs were mostly absent around EWSR1 and FLI1 loci." (PMID 41444391, 2025).
sarcoma (88 papers, 2008 to 2025). A usually aggressive malignant neoplasm of the soft tissue or bone. "This isogenic system demonstrated that EWS::FLI1 fusion is responsible for SN-38 sensitivity, highlighting the particularity of EwS biology compared to other sarcomas." (PMID 40721661, 2025). "Assessment of partner genes in EWSR1 fusion positive sarcomas found that fusion partner genes were most prevalent on chromosome 11, driven by FLI1." (PMID 34021224, 2021). "The tumor presents a genetic translocation between genes 11 and 22 (t;11:22) that gives rise to a fusion gene (Ewing sarcoma/Friend leukemia integration 1 transcription factor [EWS/FLI1]) with potent oncogenic action." (PMID 28210452, 2017). "Furthermore, they provide a strong rationale for the use of PROTACs in targeting gene fusions in paediatric sarcoma such as EWSR1::FLI1 and PAX3::FOXO1." (PMID 40983796, 2025). "Interestingly, driver fusion genes in sarcomas favor RBPs with LCDs such as EWS/FLI1 and TAF15/NR4A3." (PMID 35954475, 2022). "Importantly PDGF ligands and/or receptors are frequently upregulated in ES and their expression correlates with the activity of the EWSR1/FLI1 fusion in sarcoma tissues." (PMID 35454895, 2022). "The manner in which Ets1 regulation by PAX3/FOXO1 and EWS/Fli1 tracks with the effects of the respective oncofusions on metastatic phenotypes suggests that Ets1 may have a more general, important role in sarcoma metastasis." (PMID 32697014, 2020). "We found that PRMT1 and PRMT5 expression, along with MEP50 the obligate cofactor of PRMT5, are generally higher in multiple sarcoma types, including EWSR1::FLI1 and EWSR1::ERG fusion-positive ES tumours, than in breast and lung cancer." (PMID 40823091, 2025). "Some sarcomas have specific molecular characteristics, such as SYT::SSX fusion in synovial sarcoma, EWSR1::FLI1 fusion in Ewing's sarcoma (ES), and MDM2 amplification in dedifferentiated liposarcoma (DDLS), leading to correct diagnosis and treatment." (PMID 40755265, 2025). "An initial diagnosis of sarcoma NOS in the abdomen and trunk was classified as ES and extraskeletal myxoid chondrosarcoma (EMC) based on the fusion genes EWSR1::FLI1 and NR4A3::EWSR1, respectively." (PMID 40755265, 2025). "The FET (FUS, EWSR1, and TAF15) fusion oncogenes are characteristic for around 20 different sarcomas and leukemia, including FUS::DDIT3 in myxoid liposarcoma (MLS) and EWSR1::FLI1 in Ewing sarcoma (EWS), the two most common FET sarcoma entities." (PMID 40988026, 2025). "The best characterized example is the EWSR1-FLI1 Ewing sarcoma fusion protein, where the presence of EWSR1 allows the fusion protein to bind genomic locations that are otherwise inaccessible to wild type (wt) FLI1." (PMID 35477713, 2022). "The vast majority of CIC–DUX4 sarcomas express ERG and FLI1, as frequently as in classic ES, representing an important diagnostic challenge in differential diagnosis." (PMID 32155762, 2020). "Intimal sarcomas are comprised of epithelioid or haphazardly arranged spindled cells and express endothelial cell markers CD31 and Fli-1." (PMID 26106489, 2015). "Nine fusion genes were specific to particular histotypes, including SYT::SSX fusion in synovial sarcoma, EWSR1::FLI1 fusion in ES, EWSR1::NR4A3 fusion in EMC, BCOR::CCNB3 fusion in sarcoma with BCOR genetic alterations, and EWSR1::CREB3L1 fusion in sclerosing epithelioid fibrosarcoma." (PMID 40755265, 2025). "While FLI1 is unable to confirm EwS cases with FET–non-FLI1 translocations, NKX2-2 and PAX7 lack specificity and can be even strongly expressed in close morphological mimics such as EWSR1-NFATc2-positive sarcomas." (PMID 32164354, 2020). "The lack of FLI1 expression can be used as anadditional biomarker to differentiated between mesenchymal chondrosarcoma andEwing’s sarcoma." (PMID 31131120, 2019).
sarcoma (continued). "The paper investigates the presence of EWS/FLI-1 fusion in clinically diagnosed sarcoma belonging to different non-Ewing connective tissue tumors in order to search for a possible new biomarker valuable for investigators." (PMID 25870707, 2014). "Although these Prx-Cre;Ews-Fli1 mice developed multiple bone abnormalities, they ultimately failed to produce sarcomas." (PMID 23036318, 2012). "Furthermore, many studies highlight the promise of kinase inhibitors such as larotrectenib in treating NTRK-fusion-positive sarcomas and DNA minor groove-binding agents like trabectedin or mithramycin as potential inhibitors of EWSR1::FLI1-mediated transcription." (PMID 38228904, 2024). "Similar to the Prx-Cre;Ews-Fli1 studies, these mice did not develop sarcomas, but did display numerous congenital defects, suggesting the Pax3-Fkhr fusion gene is important in normal murine development but requires additional genetic hits for sarcoma development." (PMID 23036318, 2012). "Therefore, expression of FLI-1 alone will not lead to diagnosing sarcoma in normal situations." (PMID 38280044, 2024). "To address that, we crossed four datasets comprising: EWS::FLI1 transcriptionally regulated genes (A673/TR/shEF; 36 h DOX treatment), differentially expressed genes between EwS and non-EwS sarcoma cell lines, and two R-loop interactomes." (PMID 40721661, 2025). "Although some gene fusions are very specific to a particular tumor type (e.g. EWSR1::FLI1 in Ewing sarcoma), other gene fusions are much more non-specific, such as ETV6::NTRK3, which can be seen not only in sarcomas but also in leukemias or carcinomas." (PMID 38228904, 2024). "Among these were epithelial carcinoma cell lines (UMRC2 and 786-O), a clear cell sarcoma cell line with the oncogenic EWS::ATF1 rearrangement (SU-CCS-1), and two primary cell lines that either express FLI1 (HUVEC) or do not express FLI1 (RPTEC)." (PMID 36793594, 2023).
breast carcinoma (58 papers, 2012 to 2025). "In PE, when CS are elevated, Na/K-ATPase is depressed and Fli1 is low this results in the occurrence of a phenotype associated with a significantly lower incidence of breast cancer." (PMID 33669287, 2021). "FLI1 is associated with a poor prognosis in multiple tumors, including non-small-cell lung cancer, breast cancer, and acute myeloid leukemia." (PMID 33042835, 2020). "There was also a relatively high abundance of FLI1 in breast cancer tissues associated with metastases and in advanced stages." (PMID 30537986, 2018). "In this study, we for the first time identify FLI1 as a critical molecular factor associated with breast cancer metastasis." (PMID 26156017, 2015). "In conclusion, this study for the first time demonstrates FLI1 as a target gene that is associated with breast cancer metastasis." (PMID 26156017, 2015). "Taken together, these data suggest that the activation of this signal pathway by FLI1 may be associated with the metastatic potential of the breast cancer cells tested in this study." (PMID 26156017, 2015). "Notably, FLI1 activated the Rho GTPase pathway that is known to be associated with metastasis in breast cancer." (PMID 26156017, 2015). "Therefore, the FLI1 was considered to be significantly associated with blue module, brown module and turquoise module in breast cancer patients, which should be further investigated to understand the association between FLI1 expression level and immune gene expression level." (PMID 32249526, 2020). "In addition, up-regulation of FLI1 could activate the Rho GTPase pathway associated with breast cancer metastasis." (PMID 28286742, 2017). "For instance, FECR1 circRNA interacts with the FLI1 promoter through significant demethylation, thereby regulating the FLI1 gene, which promotes breast cancer growth and metastasis." (PMID 39239069, 2024). "FECR1 circular RNA interacts with the FLI1 promoter through extensive demethylation, which regulates the FLI1 gene in the growth of breast cancer and promotes metastasis." (PMID 37243750, 2023). "Another circRNA, FECR1, is able to simultaneously recruit TET1 and repress DNMT1 to decrease the methylation levels of the oncogene Friend leukemia virus integration 1 (FLI1), aberrantly overexpressed in various tumors, promoting metastasis in breast cancer." (PMID 36760365, 2023). "The studies reported FLI-1 overexpression in cancer and its role as an oncogene in ovarian cancer, melanoma, small-cell lung cancer, and breast cancer." (PMID 37047006, 2023). "Overall, endoglin controls and regulates DEHP-induced SIV sprouting and VEGFA expression in Tg (fli1: EGFP) embryos injected with breast cancer cells." (PMID 35203627, 2022). "The new circular RNA FECR1was identified when Chen et al10 explored the mechanism of Friend leukaemia virus integration 1 (FLI1), which was up‐regulated and acted as a tumour metastasis driver in breast cancer." (PMID 33277969, 2022). "At the same time in breast cancer patients CS and Na/K-ATPase are regular and Fli1 is high; i.e., as if patients with PE administered an anti-CS antibody." (PMID 33669287, 2021). "Fli1 attracted attention primarily because of its contribution to different types of cancer including gastric cancer, Burkitt lymphoma, breast cancer, pancreatic ductal adenocarcinoma, small cell lung cancer and Ewing’s sarcoma." (PMID 33669287, 2021). "The regulation of the FLI1 gene in the development of breast cancer occurs via the FECR1 circular RNA interacting with the FLI1 promoter through extensive demethylation, promoting metastasis." (PMID 34439334, 2021). "In an another study in 2018, a novel circular RNA FECR1 derived from FLI1 exons, was illustrated to have a positive correlation with tumor invasion in breast cancer cell lines, suggesting its role as an oncogenic driver in metastasis of breast cancer." (PMID 34335937, 2021).
breast carcinoma (continued). "CircFECR1 enhances breast cancer (BC) invasion by recruiting ten–eleven translocation 1 (TET1) to the promoter of its parental gene Friend leukemia virus integration 1 (FLI1), inducing DNA demethylation and activating transcription." (PMID 33317550, 2020). "Mechanism studies have shown that the deletion of Fli-1 can promote breast cancer growth metastasis, whereas exogenous expression of Fli-1 can significantly inhibit the breast cancer cells growth, metastasis, and invasion both in cell and mouse models." (PMID 32210104, 2020). "In breast cancer, circ-FLI1 is thought to directly recruit TET1 demethylase to the FLI1 promoter, resulting in DNA demethylation." (PMID 32878117, 2020). "Then, we compared the gene expression profile of the high expression FLI1 subtype samples with the low expression FLI1 subtype samples by the GSEA analysis to study the different TILs in these two subtypes of breast cancer." (PMID 32249526, 2020). "In this study, to examine the influence of FLI1 in immune system in breast cancer, we interrogated the relationship between the FLI1 expression levels with infiltration levels of 28 immune cell types." (PMID 32249526, 2020). "For example, two studies showed that overexpression of FLI1 promotes malignancy in breast cancer, while a different breast cancer model suggested that FLI1 acts as a tumor suppressor gene." (PMID 31231464, 2019). "Overall, FLI‐1 can induce the EMT program by regulating the promoters of EMT‐related key genes at the mRNA level in breast cancer cells." (PMID 29869379, 2018). "In highly metastatic human breast cancer cells, knockdown of FLI1 significantly attenuated tumor metastasis through the Rho GTPase pathway." (PMID 30537986, 2018). "To determine the role of FLI1 in breast cancer, we first examined its expression in tumor samples collected from patients with breast cancer." (PMID 30537986, 2018). "The Kaplan‐Meier log‐rank survival curves demonstrated that the OS and DFS of all patients with breast cancer with high expression of FLI‐1 were significantly shorter than those in patients with low expression Median survival time." (PMID 29869379, 2018). "Some ETS factors have already been proved to be dysregulated in breast cancer, but the role of FLI‐1 in breast cancer is still controversial." (PMID 29869379, 2018). "In breast cancer, aberrant expression of FLI1 correlates with advanced stage, poor differentiation, lymph node metastasis, and disease-free survival." (PMID 30537986, 2018). "In patients with breast cancer, expression of FLI1 is strongly correlated with advanced stage, poor differentiation, and lymph node metastasis." (PMID 30537986, 2018). "Using this CasIP assay, we identified FECR1, a FLI1 exonic circular RNA that binds to the FLI1 promoter and epigenetically activates FLI1 in breast cancer cells." (PMID 30537986, 2018). "Further, FLI‐1 was closely related to the recurrence and death among patients with breast cancer (P < .001)." (PMID 29869379, 2018). "A series of clinical studies from our lab showed that FLI1 is overexpressed in breast cancers and lung cancers." (PMID 30537986, 2018). "Immunohistochemical staining showed that FLI1 is aberrantly overexpressed in advanced stage and metastatic breast cancers." (PMID 30537986, 2018). "Recently, we showed that knockdown of FLI1 with small interfering RNAs significantly attenuated the potential for invasion of highly metastatic human breast cancer cells." (PMID 30537986, 2018). "In the present study, we focused on the prognostic value of FLI‐1 in patients with breast cancer and its preliminary mechanisms in the TNBC cells." (PMID 29869379, 2018). "To identify the molecular components that aberrantly regulate FLI1 in breast cancer, we utilized a novel CasIP approach to immunoprecipitate the FLI1 promoter chromatin complex." (PMID 30537986, 2018).